PTH (parathyroid hormone)
Diseases named in the same sentence as PTH in open-access papers (continued):
Sharing a sentence is not in itself a finding about the gene and the disease.
Hypocalcemia (continued). "Normally the body avoids hypocalcaemia by boosting secretion of PTH, which increases renal calcium re-absorption and calcium release from the skeleton through bone resorption." (PMID 24073266, 2013). "Although we did find group 2 had significantly lower 25-OHD level than group 1, when both 25-OHD and PTH-SC were entered into a multivariate analysis, only PTH-SC was a statistically significant factor for hypocalcemia." (PMID 22968355, 2013). "The major factors responsible for stimulating parathyroid gland function in renal failure involve hyperphosphatemia, hypocalcemia, decreased production of 1,25-dihydroxyvitamin D and peripheral resistance to parathyroid hormone (PTH)." (PMID 23603995, 2013). "Hypocalcemia, hypophosphatemia and increased PTH concentrations are known inducers of renal CYP27B1 gene expression in mice." (PMID 24019880, 2013). "Instead, the PTH-SC (OR 2.49) and parathyroid autotransplantation (OR 3.23) were the two most significant factors for hypocalcemia." (PMID 22968355, 2013). "Hypocalcemia (Low serum levels of ionized calcium) frequently happens as a result of calcium inadequate response to parathyroid hormone." (PMID 24693502, 2013). "Hyperphosphatemia also reduces Ca2+ in the circulation; the resulting hypocalcemia further stimulates PTH synthesis and secretion." (PMID 23760058, 2013). "In conclusion, PTH-SC and parathyroid autotransplantation were the two independent factors or predictors for hypocalcemia after thyroidectomy, whereas preoperative 25-OHD level was not." (PMID 22968355, 2013). "The best cutoff value in predicting hypocalcemia for PTH-SC was 1.5 pmol/L (Youden’s index 0.618, sensitivity 73.0 %, specificity 88.9 %) and for PTH-D1 was 0.9 pmol/L (Youden’s index 0.589, sensitivity 70.3 %, specificity 90.6 %)." (PMID 22968355, 2013). "The PTH measurement on the first postoperative day has been shown to be a useful method to predict post-thyroidectomy hypocalcemia." (PMID 24267491, 2013). "Thyroid surgery impairs PTH secretion by the parathyroid glands resulting in postoperative parathyroid insufficiency and subsequent development of hypocalcaemia." (PMID 24267491, 2013). "CKD leads progressively to phosphorus retention, impaired vitamin D activation, hypocalcemia, and increased parathyroid hormone (PTH) secretion." (PMID 23637579, 2013). "In the late/terminal (dysadapted ) stage, failure of these adaptive mechanisms (low IGF-I, very slow or arrested bone growth and high PTH) and significant exhaustion of bone hydroxyapatite lead to hypocalcemia." (PMID 24106607, 2013). "Serum PTH concentration, when checked 1-6 h after thyroidectomy, has a higher accuracy in predicting hypocalcaemia." (PMID 24267491, 2013). "The accuracy of PTH-SC in predicting hypocalcemia appeared similar between patients with preoperative 25-OHD <15 and ≥15 ng/mL." (PMID 22968355, 2013). "The accuracy of PTH-SC in predicting hypocalcemia was measured by area under a receiver operating characteristic curve (AUC), and the AUC of PTH-SC was compared between patients with preoperative 25-OHD <15 and ≥15 ng/mL via bootstrapping." (PMID 22968355, 2013). "Calcium is actively transported across the placenta and, when pregnancy results in a live birth, cases of profound foetal PTH suppression (with hypocalcaemia and tetany requiring intravenous calcium therapy) have been reported." (PMID 23758620, 2013). "The chance of finding subnormal i-PTH levels in patients with hypocalcemia was 4.2 to 7 times greater than the chance of observing altered test results in individuals with normal calcium levels." (PMID 23108824, 2012). "Transient hypocalcemia is one of the postoperative complications of thyroidectomy for thyroid nodules, and intraoperative and postoperative intact parathyroid hormone (iPTH) assays are used to predict postoperative hypocalcemia." (PMID 23843829, 2012).
Hypocalcemia (continued). "The possible reasons are that hypocalcaemia stimulates secretion of parathyroid hormone to increase blood calcium and enhance osteolytic cells to break bone, resulting in osteoporosis, which provides opportunity for cancer cells invasive the bones." (PMID 22479582, 2012). "Among the various strategies proposed to optimize the management of postoperative hypocalcemia by shortening hospital stay, PTH-directed selective supplementation is a safe and effective approach." (PMID 22399155, 2012). "Pseudohypoparathyroidism (PHP) is characterized by hypocalcemia, hyperphosphatemia, and an elevated serum parathormone (PTH) level due to peripheral PTH resistance." (PMID 22394705, 2012). "This retrospective case series studied a group of 110 consecutive for hypocalcemia and intact parathyroid hormone (PTHi) levels four and twelve hours following total thyroidectomy." (PMID 23108824, 2012). "Preoperative Ca level and PTH-SC were the two most significant determinants of hypocalcemia after total or completion thyroidectomy." (PMID 22399155, 2012). "Briefly, hypocalcemia leads to increased PTH secretion, which stimulates renal calcium reabsorption and bone resorption." (PMID 23202962, 2012). "Intact parathyroid hormone (iPTH) assay, intraoperative and postoperative, is used to predict postoperative hypocalcemia development following total thyroidectomy for various thyroid diseases." (PMID 23843829, 2012). "This study looked into the correlations between i-PTH serum levels measured at different times in post-thyroidectomy care and the occurrence of symptomatic hypocalcemia." (PMID 23108824, 2012). "The association of our patient's symptoms and physical findings of hypocalcemia and hyperphosphatemia with a low PTH are consistent with the diagnosis of hypoparathyroidism." (PMID 22251708, 2012). "His posttreatment PTH level of 12 pmol/L (1.6–7.2) suggests secondary hyperparathyroidism due to hypocalcaemia." (PMID 23213582, 2012). "In predicting hypocalcemia, the best cutoff values for PTH-SC and PTH-D1 were ≤1.0 pmol/L (Youden’s index = 0.774; sensitivity 82.4 % and specificity 95.0 %) and ≤0.6 pmol/L (Youden’s index = 0.695; sensitivity 76.5 % and specificity 93.0 %), respectively." (PMID 22399155, 2012). "Statistical analysis was used to evaluate the performance of isolated and serial i-PTH measurements to determine the likelihood of symptomatic hypocalcemia." (PMID 23108824, 2012). "We prospectively evaluated the accuracy and reliability of quick parathyroid hormone level measurement at skin closure (PTH-SC) in predicting clinically relevant hypocalcemia (i.e., patients requiring calcium ± calcitriol supplements on hospital discharge)." (PMID 22399155, 2012). "In contrast, secondary hyperparathyroidism is characterized by hypocalcaemia leading to a compensatory increase in secretion of PTH." (PMID 23227372, 2012). "The levels of i-PTH at different points in postoperative care were highly sensitive (90.3% to 96.8%) for symptomatic hypocalcemia, while specificity ranged between 77.2% and 87.3%." (PMID 23108824, 2012). "Renal 1,25(OH)2D production in humans is normally enhanced by PTH, hypocalcaemia, and hypophosphatemia and inhibited by 1,25(OH)2D and fibroblast growth factor 23 (FGF23)." (PMID 21731765, 2011). "Breast-feeding of neonatal 1α(OH)ase−/− pups with milk containing a higher calcium and low level of 1,25(OH)2D3 had less severe hypocalcemia and subsequent less elevation of serum PTH compared to adult mutant mice." (PMID 21966280, 2011). "The hyperphosphatemia, hypocalcemia, and decreased levels of active vitamin D result in increased synthesis and secretion of parathyroid hormone." (PMID 22152332, 2011). "Magnesium is also involved in the metabolism and activity of vitamin D. Patients with hypocalcemia and hypomagnesemia are resistant to large doses of vitamin D, because of reductions in PTH secretion and renal resistance to this hormone." (PMID 21181066, 2010).
Hypocalcemia (continued). "Parathyroid hormone (PTH) is a major regulator of calcium metabolism which defends against hypocalcemia, in part by stimulating bone resorption and thereby the release of calcium from the skeleton." (PMID 20808842, 2010). "The decrease in vitamin D activation induces hypocalcemia and a subsequent increase in PTH secretion to maintain serum Ca levels normal but induces a high level of bone turnover and hyperphosphatemia." (PMID 21234310, 2010). "An abrupt fall in calcium concentration leads to reduction of the production and release of parathormone (PTH) and exacerbates the secondary clinical manifestations, because of hypocalcemia." (PMID 21181066, 2010). "Pseudohypoparathyroidism (PHP), also known as Albright’s hereditary osteodystrophy (AHO), refers to a heterogeneous group of rare metabolic disorders characterized by hypocalcemia and hyperphosphatemia due to parathyroid hormone (PTH) resistance." (PMID 21274345, 2010). "As part of APS1, hypoparathyroidism occurs in 80% of patients and is characterized by hypocalcemia, hyperphosphatemia, and low serum levels of PTH." (PMID 19580466, 2010). "Children with PHP present with hypocalcemia and normal or elevated serum phosphorus (P) concentrations despite elevated serum PTH levels." (PMID 21274319, 2010). "For patients with undetectable PTH level, oral calcium and vitamin D analogue should be administered early to avoid symptomatic hypocalcaemia." (PMID 20798772, 2010). "A normal PTH can predict normocalcaemia, and patients can be discharged early with 7% subsequently developing mild hypocalcaemia." (PMID 20798772, 2010). "Considering the association of KSS with hypoparathyroidism, our patient presented with hypocalcemia at 4 years of age and the hypoparathyroidism was proven by reduced serum concentrations of parathyroid hormone (PTH) and hyperphosphatemia." (PMID 19946579, 2009). "Pseudohypoparathyroidism (PHP) represents a heterogeneous group of disorders characterized by end−organ unresponsiveness to PTH leading to hypocalcemia, hyperphosphatemia, and elevated PTH concentrations." (PMID 21274302, 2009). "The binding of these proteins to the PTH mRNA 3'-UTR is regulated in the parathyroid by chronic hypocalcemia, hypophosphatemia and experimental kidney failure as well as by the calcimimetic R568." (PMID 19397786, 2009). "The parathyroid glands respond initially to the low calcium levels by increasing PTH secretion and synthesis, but prolonged hypocalcemia leads to parathyroid gland hyperplasia." (PMID 19924035, 2009). "Reflecting the tissue-specific silencing of paternal Gsα in the proximal tubule, PTH-resistance, characterized by hypocalcemia, hyperphosphatemia, and elevated serum PTH, is present only after maternal inheritance of the disrupted allele." (PMID 19412439, 2007). "Some patients present with asymptomatic hypocalcemia and inappropriately low parathyroid hormone levels that leads to fluorescence in situ hybridization and the diagnosis of chromosome 22q11.2 deletion syndrome." (PMID 18053182, 2007). "His initial laboratory examination showed hypocalcemia (Calcium 5.2 mg/dl and Calcium ionized 0.69 mmol/l) with hypoparathyroidism (Parathyroid hormone intact < 2.5 pg/ml." (PMID 18053182, 2007). "Since the first reports of adverse bone effects of AEDs more than 3 decades ago, a number of biochemical abnormalities of bone metabolism have been reported with AED use including hypocalcemia, hypophosphatemia, low vitamin D levels and increase in PTH." (PMID 16956398, 2006). "Elevated PTH levels, either as primary abnormality or as a compensatory response to hypocalcemia, can activate osteoclastic bone resorption to maintain normocalcemia." (PMID 16956398, 2006). "Importantly, the observed episodes of hypocalcemia, despite the marked rise in PTH, suggests that the compensatory mechanism was insufficient to counteract ongoing calcium depletion." (PMID 40663633, 2026).
Hypocalcemia (continued). "This is associated with inhibition of the Transient Receptor Potential Cation Channel, Subfamily M, Member 6 -TRPM6 channel, which leads to urinary magnesium leakage and hypomagnesemia, subsequently stopping PTH secretion and resulting in hypocalcemia and hypocalciuria." (PMID 41751411, 2026). "Postoperative PTH levels serve as excellent predictors of hypocalcemia." (PMID 40671592, 2026). "Evaluation revealed profound hypocalcemia with low ionized calcium, persistent hypomagnesemia, low 25-hydroxyvitamin D, and markedly elevated parathyroid hormone (PTH), consistent with a multifactorial metabolic derangement including vitamin D deficiency-associated secondary hyperparathyroidism." (PMID 42266327, 2026). "Laboratory evaluation revealed severe hypocalcemia with undetectable parathyroid hormone levels." (PMID 41625059, 2026). "Various predictors of immediate postthyroidectomy hypocalcemia have been identified, including single postoperative intact PTH values, percentage decrease of intact PTH from baseline, 25-hydroxyvitamin D levels, and underlying thyroid disorders such as Graves’ disease." (PMID 40671592, 2026). "Second, an acute increase in PTH, potentially triggered by transient hypocalcemia during TPE, may have stimulated rapid FGF-23 production." (PMID 40663633, 2026). "Notably, recent studies propose that %PTH (the percentage decay between Pre-PTH and PTH at skin closure) predicts hypocalcemia following thyroidectomy." (PMID 40979702, 2025). "Initial investigations revealed hypocalcemia with elevated PTH, indicating PTH resistance." (PMID 41170251, 2025). "Evidence suggests that chronic hypocalcemia with relative hyperphosphatemia in hypoparathyroidism and disordered calcium-phosphate-PTH balance in CKD-MBD (typically secondary hyperparathyroidism) may lower the threshold for basal ganglia mineralization." (PMID 41531582, 2025). "For severe hypocalcemia, univariate analysis suggested that age, whether to perform prophylactic intravenous calcium supplementation, and preoperative PTH, calcium and preoperative ALP level were potentially associated with it (P<0.05)." (PMID 41367906, 2025). "Although renal insufficiency can theoretically lead to hypocalcemia and hyperphosphatemia, thereby stimulating PTH secretion and elevating PTH levels, in this patient, renal dysfunction progressed gradually, with no acute deterioration coinciding with the PTH elevation." (PMID 41561737, 2025). "However, if low-level endotoxin exposure persists and drives a chronic inflammatory state, the inflammatory cytokines (such as IL-1 and IL-6) can suppress PTH secretion and disturb vitamin D metabolism, thereby perpetuating a cycle of hypocalcemia." (PMID 40284849, 2025). "The biochemical findings and symptomatology therefore resemble hypoparathyroidism with hypocalcemia and hyperphosphatemia but instead of low PTH levels the patients usually have high PTH levels with or without physical features of Albright hereditary osteodystrophy (AHO)." (PMID 41322012, 2025). "This form of hyperparathyroidism is characterized by adequate PTH secretation due to hypocalcemia." (PMID 41301699, 2025). "Additionally, when ROC was performed by Jakubauskas, the 45 pmol/L (424.3 pg/mL) cut‐off value of the preoperative PTH level was reported to have the highest sensitivity and specificity to predict the development of postoperative hypocalcemia." (PMID 40517023, 2025). "Laboratory findings consistently revealed hypocalcemia and low parathyroid hormone (PTH) levels." (PMID 40590356, 2025). "Blood tests showed hypocalcemia (6.8 mg/dL) and low intact parathyroid hormone (PTH) (14 pg/mL), as well as low urinary calcium to creatinine ratio (0.0005 mg/mg) and normal levels of 25-OH Vitamin D and serum magnesium, leading to the diagnosis of tetany secondary to hypoparathyroidism." (PMID 41164028, 2025). "At present, the method most commonly used to predict hypocalcemia is the PTH test." (PMID 40786097, 2025).
Hypocalcemia (continued). "In addition, rabbits diagnosed with acquired dental disease showed evidence of hypocalcemia accompanied by elevated serum parathyroid hormone levels." (PMID 40654513, 2025). "However, individuals with insufficient PTH secretion or PTH action are prone to hypocalcemia in such periods." (PMID 41164028, 2025). "Foscarnet-induced ionized hypomagnesemia may hinder preformed parathyroid hormone (PTH) excretion or cause target organ resistance, potentially resulting in ionized hypocalcemia." (PMID 40291321, 2025). "It is well-known that an increase in serum phosphorus levels may promote PTH secretion by the induction of hypocalcemia, inhibition of 1,25-dihydroxy vitamin D synthesis, and direct stimulation of PTH synthesis and secretion." (PMID 40922882, 2025). "Biochemical analysis revealed markedly elevated parathyroid hormone (192.5 pg/mL; normal 15-65 pg/mL) with hypocalcaemia (2.0 mmol/L; normal 2.2-2.6 mmol/L) and profound vitamin D deficiency (20 nmol/L; sufficient >50 nmol/L), consistent with secondary hyperparathyroidism." (PMID 41257110, 2025). "Peri-operative PTH level is a good predictor of post-thyroidectomy hypocalcaemia." (PMID 40519462, 2025). "Both patients exhibited typical features of PTH resistance, including biochemical hypocalcemia with markedly elevated iPTH levels (177.7 and 330 pg/mL, respectively), as well as clinical findings of short stature, brachydactyly, round face, and skeletal anomalies." (PMID 41155848, 2025). "This case highlights delayed recognition of a rare cause of symptomatic hypocalcemia and emphasizes early and careful interpretation of basic biochemical tests (P, Mg, ALP), endocrine tests (PTH, TSH, fT4, active vitamin D), and imaging tests (bone X-ray, brain CT), to investigate the cause." (PMID 41322012, 2025). "Similarly, parenteral antiresorptive agents can lead to hypocalcemia due to reduced bone calcium mobilization, increasing parathyroid hormone (PTH) secretion, and exacerbating kidney phosphate excretion." (PMID 41445550, 2025). "Although PTH promotes renal phosphorus excretion to prevent hyperphosphatemia, serum phosphorus may initially rise during early hypocalcemia." (PMID 40431588, 2025). "Subtle features such as hypothyroidism and persistent nonresponsive hypocalcemia to medication should raise concerns of more rare causes, including PTH resistance, supported by the biochemical pattern, confirmed by genetic studies." (PMID 41181744, 2025). "These antibodies likely disrupt calcium homeostasis through dual mechanisms: i) suppressing parathyroid cell proliferation, and ii) impairing PTH synthesis/secretion, resulting in the characteristic biochemical triad of hypocalcemia, hyperphosphatemia, and inappropriately low PTH levels." (PMID 40590356, 2025). "Although administering a calcium bolus may temporarily normalize plasma calcium, cytokines such as IL-1 and IL-6 can sustain a cycle of suppressed PTH and disrupted vitamin D metabolism, thus perpetuating hypocalcemia." (PMID 40284849, 2025). "Further studies revealed that a single homozygous Arg-to-Cys mutation in residue 25 of PTH (PTHR25C), which causes severe chronic hypocalcemia (low blood Ca2+ level) in humans, is defective in inducing endosomal cAMP production in cells and serum Ca2+ elevation in mice." (PMID 41203134, 2025). "PTH suppression due to severe hypomagnesaemia induced by cetuximab leads to hypocalcemia." (PMID 40291321, 2025). "Several mechanisms may contribute to the development of hypocalcemia in trauma patients, including citrate chelation, acidosis, and parathyroid hormone dysfunction." (PMID 40098024, 2025). "Hypocalcemia was observed in over a quarter of patients, consistent with prior studies demonstrating that ionized calcium frequently falls during systemic inflammatory states due to cytokine-mediated alterations in parathyroid hormone activity." (PMID 41246592, 2025).